NLRP3 (NLR family pyrin domain containing 3)
Diseases named in the same sentence as NLRP3 in open-access papers (continued):
Sharing a sentence is not in itself a finding about the gene and the disease.
diabetes (continued). "In contrast to NLRP3-deficient C57BL/6 mice, AIM2-deficient C57BL/6 mice had accelerated STZ-induced diabetes development, compared to wild-type control mice, implying that ASC regulates inflammasome activation." (PMID 34177937, 2021). "Understanding the mechanism by which lncRNA regulates NLRP3 inflammasome is significant to discover novel therapeutic targets for diabetes and its complications." (PMID 35087834, 2021). "TXNIP has been reported to play a vital part in diabetes during the immune response by activating the inflammatory pathway via the NLRP3 (NOD-, LRR-, and pyrin domain–containing protein 3) inflammasome." (PMID 33803178, 2021). "Previous studies have shown that NLRP3 is expressed in a variety of cells and its mediated signaling pathway plays an important role in the progression of diabetes." (PMID 34823419, 2021). "The NLRP3 inflammasome also makes a significant contribution during the development of diabetes and its complications." (PMID 33546399, 2021). "First of all, the aberrant activity of the NLRP3 inflammasome promotes the pathogenesis of diabetes and obesity that is related to insulin resistance." (PMID 34070553, 2021). "It is believed that the in-depth study of the relationship between ERS and NLRP3 in diabetes will provide a new strategy for the treatment of diabetes." (PMID 33937267, 2021). "Toll-like receptors and the Nod-like receptor protein-3 (NLRP3) inflammasome, as well as interleukin-1β, all appear to participate in the pathogenesis of diabetes." (PMID 34054346, 2021). "Studies have shown that ERS is closely related to NLRP3 inflammasome in many diseases including diabetes." (PMID 33937267, 2021). "A long-term inflammatory response, oxidative stress, and release of ROS, as well as activation of subsequent NLRP3 inflammasome signaling, are significantly involved in the pathogenesis of diabetes." (PMID 34055976, 2021). "Recent studies investigated NOD-like receptor family pyrin domain-3 (NLRP3) inflammasome-mediated inflammation and pyroptosis in diabetes and its complications." (PMID 34803664, 2021). "Growing evidence suggests that exposure to environmental endocrine disruptors and activation of NLRP3 inflammasome signaling play a vital role in diabetes." (PMID 34055976, 2021). "This review summarizes the mechanism by which lncRNAs contribute to the development of diabetes and its complications by regulating NLRP3 inflammasome." (PMID 35087834, 2021). "Recently, metformin has been confirmed to regulate lncRNA-mediated NLRP3 inflammasome in diabetes complications." (PMID 35087834, 2021). "MCC950, as an inhibitor of NLRP3 inflammasome, has been demonstrated to be a compelling treatment for diabetes in mouse models." (PMID 34707607, 2021). "Nuclear factor (NF)-κB and nucleotide-binding oligomerization domain (NOD)-like receptor protein 3 (NLRP3) are thought to be two key regulators in inflammatory response in diabetes." (PMID 34326777, 2021). "Neferine (NE), suggesting that NLRP3 inflammasome is involved in diabetes-induced memory and cognitive impairment." (PMID 33937267, 2021). "This was later supported by the phenotype of greater glucose tolerance and insulin sensitivity in NLRP3-/- mice, which protect the mice from diet-induced obesity and diabetes." (PMID 34631209, 2021). "In this review, we focus on the regulatory mechanisms of NLRP3 inflammasome in diabetes and the recent advances of natural compounds derived from herbal medicine in the management of diabetes and diabetic complications via inhibiting NLRP3 inflammasome." (PMID 34631209, 2021). "The NLRP3 inflammasome is involved in the development of diabetes, which is characterized by chronic elevation of blood glucose." (PMID 34210954, 2021). "As an upstream regulator of NLRP3 inflammasome, lncRNA can exert control over diabetes and its complications." (PMID 35087834, 2021).
diabetes (continued). "Metformin can inhibit the NLRP3 inflammasome activation in ApoE-/- mice and inhibit diabetes-accelerated AS, at least in part by activating AMPK and regulating thioredoxin-1/thioredoxin interacting protein." (PMID 34163481, 2021). "Coptisine ameliorates oxidative injury in diabetic nephropathy by regulating the Nrf2 signaling pathway, and liquiritigenin inhibits diabetes-induced mesangial matrix accumulation in diabetic nephropathy by decreasing the NF-κB and NLRP3 inflammasome." (PMID 34381354, 2021). "The abnormal activation of NLRP3 inflammasome can lead to a variety of diseases including sterile inflammatory diseases, diabetes, and non-alcoholic fatty liver diseases." (PMID 33937267, 2021). "In summary, our data suggested that empagliflozin protects the pancreatic tissues from diabetes mellitus-induced injury by downregulating the NLRP3/caspase-1/GSDMD pyroptosis-related inflammasome pathway." (PMID 34823419, 2021). "The activation of NLRP3 inflammasome is closely related to the pyrocytosis, which is involved in diabetes." (PMID 33937267, 2021). "It has been demonstrated that the abnormal activation of the NLRP3 inflammasome is closely related to multiple metabolic diseases driven by aging and chronic inflammation, such as diabetes, obesity, and gout." (PMID 34646239, 2021). "Zoledronic acid increases the expression of IL-1β in an NLRP3/caspase-1-dependent manner in LPS-primed BMDMs from mice with diabetes mellitus, and NLRP3 inhibitors improve oral wound healing and suppress osteonecrosis of the jaw in these mice." (PMID 34177950, 2021). "This review summarizes the recent researches about the effects of ERS on NLRP3 inflammasome and the related mechanism in diabetes to provide ideas for the relevant basic research in the future." (PMID 33937267, 2021). "As HF and diabetes are recognised inflammatory conditions, with reports of enhanced activation of the NLRP3 inflammasome, we will also consider evidence linking microtubule organisation, inflammation and the association to mitochondrial motility." (PMID 34277734, 2021). "Activation of the NOD-, LRR- and pyrin domain-containing protein 3 (NLRP3) inflammasome plays an important role in high glucose-induced endothelial dysfunction in patients with type 2 diabetes mellitus (T2DM)." (PMID 33397395, 2021). "NLRP3 inflammasome activation induces insulin resistance and impairs pancreatic β-cells, participating in the development of diabetes." (PMID 34512671, 2021). "NLRP3 inflammasome is a complex of several proteins that play a critical role in inflammatory response and various diseases, including diabetes and its complications." (PMID 35087834, 2021). "Activated NLRP3 inflammasome plays a crucial role in the pathogenesis of HF in diabetes, resulting in amplification and infiltration of inflammatory cell, whereas a decrease in NLRP3 attenuates cardiomyopathy in a T2DM rat model." (PMID 34277669, 2021). "Our results showed that ISO pretreatment ameliorates stroke-induced retinal injury in diabetes via inhibition of retinal NLRP3 inflammasome activation." (PMID 34305534, 2021). "Our study demonstrated that MFG-E8 promotes wound healing in diabetes by regulating “NLRP3 inflammasome-NETs” axis." (PMID 32963812, 2020). "Recently, several studies have shown that adiponectin and adiponectin receptor agonist (adipoRon) exhibit protective effects against diabetes-related vascular disorders or nephropathy by suppressing NLRP3 activation." (PMID 33251225, 2020). "NLRP3 inflammasome hyperactivation in diabetes, pyroptosis, and low-grade inflammation lead to a delay of INF-γ response and lower CD4+ and CD8+ cell numbers." (PMID 33329516, 2020). "NLRP3, IL-1β, reactive oxygen species (ROS), and TXNIP are implicated in the type 2 diabetes mellitus (T2DM) pathogenesis." (PMID 32187211, 2020). "Results showed that diabetes promoted activation of the NLRP3 inflammasome regulated by oxidative stress to induce hepatocyte pyroptosis." (PMID 33692776, 2020).
diabetes (continued). "First, MFG-E8 is an endogenous inhibitor of NLRP3 inflammasome-induced IL-1β/IL-18 production in wound site of diabetes." (PMID 32963812, 2020). "This study elucidates the detailed mechanism of HG-initiated HASMC calcification through NLRP3/caspase 1/IL-1β inflammasome and indicates a potential therapeutic role of 6-shogaol in vascular calcification complication of diabetes." (PMID 31938471, 2020). "Myr administration also resulted in a lessening of diabetes-induced NLRP3 inflammasome activation and enhanced antioxidant enzyme activities." (PMID 32282828, 2020). "In a cohort study on the relationship among diabetes, AS and NLRP3 activation in human patients, the authors found that the expression of NLRP3 pathway genes was significantly higher in patients with diabetes." (PMID 32966239, 2020). "Further studies are needed to investigate the role of the NLRP3 inflammasome in macrophages in the setting of diabetes." (PMID 32118048, 2020). "As it is well-established that not only kidney failure but also hypertension triggers the NLRP3 inflammasome induction, we matched HD and BP patients taking age, gender, and diabetes mellitus into account." (PMID 33114648, 2020). "Utilizing wound model of STZ-induced diabetic WT and Mfge8−/− mice, our study is the first to demonstrate that MFG-E8 accelerates angiogenesis and wound closure in diabetes by modulating the “NLRP3 inflammasome-NETs” inflammatory loop." (PMID 32963812, 2020). "Excessive generation of reactive oxygen species (ROS) and NOD-like receptor protein 3 (NLRP3) inflammasome activation trigger the inflammation and pyroptosis in diabetes." (PMID 32842536, 2020). "Other studies have confirmed that glibenclamide and metformin, both of which are typical treatments for diabetes, have the potential to inhibit the activation of the NLRP3 inflammasome, indirectly indicating that the NLRP3 inflammasome is associated with T1DM." (PMID 32973739, 2020). "Diabetes increases pyroptosis, which is initiated by upregulation of NLRP3 (nod-like receptor family pyrin domain containing-3) that forms an inflammasome complex with ASC (apoptosis-associated speck-like protein)." (PMID 32170070, 2020). "Apart from this, DPP-4 inhibitors are also found to suppress diabetes-induced activation of NLRP3 inflammasome that induces metabolic inflammation and insulin resistance." (PMID 32282828, 2020). "Excessive activation of P2RX7 and NLRP3 leads to increased inflammatory cytokine secretion, such as IL-1β in depression and diabetes." (PMID 32842536, 2020). "After treatment with metformin in diabetes-susceptible B4 cells, the expression of nutrition excess-induced innate immunity/inflammasome molecules was ameliorated, including MDA5, NLRP3, caspase-1, and IL-1β." (PMID 32849261, 2020). "In this review, we elaborate the definition and epidemiology of depression, diabetes, and diabetic depression and introduce the functional characteristics of an NLRP3 inflammasome and upstream P2X7 receptor." (PMID 32166013, 2020). "The P2X7-mediated activation of NLRP3 inflammasome plays an important role in the onset and progression of diabetes and depression." (PMID 32166013, 2020). "In conclusion, nutraceuticals represent a promising strategy for improving metabolic abnormalities, such as diabetes, thanks to their capacity to decrease inflammation by modulating NLRP3 inflammasome and its downstream pathways." (PMID 32650482, 2020). "For example, the NLRP3 inflammasome detects signals produced by metabolism, such as increased extracellular glucose levels, which is an essential manifestation of diabetes." (PMID 32973739, 2020). "Diabetic nephropathy is characterized by typical aseptic inflammation, and the role of inflammasomes in diabetes has also been discovered, as NLRP3 activation was found in diabetic patients as well as podocytes and endothelial cell injury." (PMID 32175320, 2020).
diabetes (continued). "During impaired healing associated with diabetes, macrophages exhibits sustained NACHT, LRR, and PYD domains-containing protein 3 (NLRP3) inflammasome activity and release of IL-1β and IL-1810." (PMID 32963812, 2020). "Due to its pro-inflammatory role, the NLRP3 inflammasome has progressively become an important molecular target to cope with different chronic diseases, including myocardial infarction and diabetes." (PMID 31652822, 2019). "We demonstrated that GlcN inhibited the NLRP3 inflammasome, machinery that plays important roles in the pathogenesis of diabetes and atherosclerosis." (PMID 30944389, 2019). "We next analyzed NLRP3, an inflammasome which plays an important role in the pathogenesis of diabetes, cardiovascular, and kidney inflammatory injury through reactivating multiple inflammatory responses including apoptosis." (PMID 31448581, 2019). "Overall, this is the first study that demonstrates a relationship between mDNA, vascular NLRP3 inflammasome activation, Ca2+ influx-induced ROS generation and endothelial dysfunction in diabetes." (PMID 32009974, 2019). "Studies with a selective NLRP3 inhibitor to prevent or cure stroke occurring concomitant with diabetes are eagerly awaited." (PMID 31174550, 2019). "The use of the NLRP3 inhibitor in vitro partially attenuated the impairment of the vasodilation response in the mice with diabetes." (PMID 31817997, 2019). "Because of the detrimental role of sustaining sterile inflammation in diabetes and ischemic stroke, efforts have been made to develop NLRP3 inflammasome inhibitors against these diseases, including MCC950, glyburide, and others." (PMID 31174550, 2019). "TLR2 and NLRP3 inflammasome activation in heart macrophages induce the production of IL-1β in diabetes mellitus mice." (PMID 31354731, 2019). "This review summarizes recent progress regarding the NLRP3 inflammasome as a potential treatment for ischemic stroke in patients with diabetes, two complicated diseases that often occur together." (PMID 31174550, 2019). "Our previous study have also found that caspase-1-dependent pyroptosis induced by NLRP3 inflammasome activation contributed to diabetic myocardium and aggravated MI/R injury in diabetes." (PMID 30911553, 2019). "NLRP3 inflammasome responds to a variety of infectious and endogenous ligands and is involved in a variety of autoimmune diseases, such as obesity, diabetes mellitus, arthritis, and Alzheimer’s disease." (PMID 31835423, 2019). "Diabetes significantly increased the level of the NLRP3 subunit (p < 0.05), while the escalating effect of LPS (1 μg/ml, 24 h) was observed only in the control cultures (p < 0.05)." (PMID 31197747, 2019). "Previous research has indicated that NLRP3 inflammasome activation is one of the key contributors to impaired wound healing in diabetes." (PMID 31736762, 2019). "In this review, we summarize the present understanding of the composition, activation, and regulation of the NLRP3 inflammasome, and its potential therapeutic roles in ischemic stroke occurring concomitant with diabetes (referred to as diabetic-stroke)." (PMID 31174550, 2019). "A recent finding now suggests that oxidative stress is not only a crucial driver of inflammation, but these disturbances also induce activation of the NLRP3 inflammasome in diabetes and complications of diabetes." (PMID 31174550, 2019). "In recent years, the NLRP3 inflammasome became a research focus in a series of diseases, such as diabetes, neurodegenerative disorders, and brain trauma." (PMID 30918581, 2019). "Our results indicate that diabetes increases the levels of NFκB, NLRP3 inflammasome, and IL-1β in the hippocampus, suggesting that activation of diabetes-induced NLRP3 and enhanced secretion of IL-1β contribute to the progression of diabetic encephalopathy." (PMID 30911292, 2019).
diabetes (continued). "In this context, several research efforts have been made to investigate the effects of NLRP3 gene deletion and its components in pre-clinical models of obesity and diabetes." (PMID 31200447, 2019). "As such, further study of the interaction between the NLRP3 inflammasome and the complex intestinal environment in disease development is warranted to discover novel therapies for the treatment of diabetes." (PMID 31835423, 2019). "Given the apparent synergistic adverse effects of ischemic stroke and diabetes, it is important to determine how these diseases are related and explore potential therapies such as the NLRP3 inflammasome." (PMID 31174550, 2019). "With diabetes, NLRP3 is stimulated by the ER stress and cleaves and stimulates caspase-1, leading to secretion and release of the pro-inflammatory cytokines IL-1β and IL-18." (PMID 30657794, 2019). "In this review, we summarized the composition and activation of NLRP3 inflammasomes and their potential therapeutic role in the progression of diabetes." (PMID 31835423, 2019). "WMW inhibits the activation of the NLRP3 inflammasome to protect pancreatic β cells and prevent type 2 diabetes mellitus development." (PMID 30704457, 2019). "Vitamin D3 decreases diabetes-induced ROS and exerts protective effects against retinal vascular damage and cell apoptosis in association with inhibition of the ROS/TXNIP/NLRP3 inflammasome pathway." (PMID 29682582, 2018). "This review addresses these latest findings with an aim of highlighting the interconnectivity between oxidative stress, NLRP3 activation and inflammation as it pertains to cardiac, vascular and renal injury sustained by diabetes." (PMID 29515457, 2018). "This review will address these latest findings with an aim of highlighting the interconnectivity between oxidative stress, NLRP3 activation and inflammation as it pertains to cardiac and vascular injury sustained by diabetes." (PMID 29515457, 2018). "In our logistic regression with covariants, the reduction in total methylation or some CpGs methylation in the NLRP3, AIM2 and ASC promoters increased the risk of diabetes or diabetic vascular complications to a varying degree." (PMID 30555415, 2018). "Activation of NOD-like receptor protein 3 (NLRP3) inflammasome participates in the development of diabetes, and contributes to renal ischemia-reperfusion injury." (PMID 30114208, 2018). "Na+ loading contributes to elevated oxidative stress and activation of the NLRP3 inflammasome (inflammation), consequently leading to the development of diabetes in humans." (PMID 30519189, 2018). "Nevertheless, these findings clearly provide a rationale to further study SGLT2 inhibition on NLRP3 inflammasome activation in diabetes patients, and represents a target with considerable therapeutic promise." (PMID 29515457, 2018). "Our study investigated the inhibitory roles of Gas in ER stress and NLRP3 inflammasome activation in response to diabetes, indicating its neuroprotective effects on diabetic encephalopathy." (PMID 30544722, 2018). "In the present study, we found that the activation of NLRP3 inflammasome significantly increased in a ROS-dependent manner to induce pyroptotic cell death during MI/R injury in diabetes." (PMID 29062465, 2017). "Activation of the NLRP3 inflammasome promotes renal injury through the up-regulation of IL-1β and IL-18, and enhances IL-1β production in diabetes." (PMID 28708885, 2017). "We reconfirmed that NLRP3 inflammasome activation-mediated pyroptosis aggravated MI/R injury in diabetes." (PMID 29062465, 2017). "PIO significantly attenuated the diabetes-induced activation of the NLRP3 inflammasomes and their downstream effectors, including caspase-1, IL-1β, and IL-18." (PMID 28708885, 2017).